PRRX1 (paired related homeobox 1)
Description:
Master transcription factor of stromal fibroblasts for myofibroblastic lineage progression. Orchestrates the functional drift of fibroblasts into myofibroblastic phenotype via TGF-beta signaling by remodeling a super-enhancer landscape. Through this function, plays an essential role in wound healing process. Acts as a transcriptional regulator of muscle creatine kinase (MCK) and so has a role in the establishment of diverse mesodermal muscle types. The protein binds to an A/T-rich element in the muscle creatine enhancer (By similarity). May play a role in homeostasis and regeneration of bone, white adipose tissue and derm (By similarity). [Isoform 1]: Transcriptional activator, when transfected in fibroblastic or myoblastic cell lines. This activity may be masked by the C-terminal OAR domain. [Isoform 2]: Transcriptional repressor, when transfected in fibroblastic or myoblastic cell lines.
Synonyms: PRX-1; PMX1; PHOX1; AGOTC; PRX1
Tractability: No criterion of Open Targets' tractability assessment is met for any kind of drug.
Gene: Protein-coding gene on chromosome 1 (170,662,728 to 170,739,421, forward strand). Ensembl gene ENSG00000116132.
Subcellular location: Nucleus
Subcellular location (Human Protein Atlas): Nucleoplasm
Gene Ontology:
Molecular function: DNA-binding transcription activator activity, RNA polymerase II-specific; protein binding; RNA polymerase II cis-regulatory region sequence-specific DNA binding; RNA polymerase II-specific DNA-binding transcription factor binding; DNA-binding transcription factor activity, RNA polymerase II-specific; DNA binding; DNA-binding transcription repressor activity, RNA polymerase II-specific; HMG box domain binding; RNA polymerase II general transcription initiation factor activity
Biological process: positive regulation of transcription by RNA polymerase II; regulation of transcription by RNA polymerase II; negative regulation of transcription by RNA polymerase II; regulation of DNA-templated transcription; transcription by RNA polymerase II
Cellular component: nucleoplasm; chromatin; nucleus
Genetic constraint (gnomAD): Loss-of-function variants: 8 observed, 25.28 expected, observed/expected ratio (o/e) 0.32, 90% interval 0.19 to 0.57. The upper end of that interval is the gene's LOEUF score, 0.57, which puts it in group 2 of 6, group 1 being the genes least tolerant of losing a copy. Missense variants: 281 observed, 341.3 expected, observed/expected ratio (o/e) 0.82, 90% interval 0.75 to 0.91. Synonymous variants: 160 observed, 138.93 expected, observed/expected ratio (o/e) 1.15, 90% interval 1.01 to 1.31.
Homologues: Orthologues: chimpanzee PRRX1 (100% identical), macaque PRRX1 (100% identical), dog PRRX1 (99% identical), mouse Prrx1 (99% identical), pig PRRX1 (99% identical), rat Prrx1 (99% identical), guinea pig PRRX1 (99% identical), rabbit PRRX1 (91% identical), tropical clawed frog prrx1 (89% identical), zebrafish prrx1a (84% identical), zebrafish prrx1b (84% identical), Drosophila melanogaster CG9876 (35% identical). Paralogues in human: PRRX2 (61% identical), ARX (33% identical), RAX (33% identical), ALX4 (31% identical), ALX3 (29% identical), PAX7 (29% identical), PHOX2B (29% identical), ALX1 (29% identical), PHOX2A (29% identical), VSX2 (29% identical), DMBX1 (28% identical), OTP (28% identical), and 38 more.
Diseases named in the same sentence as PRRX1 in open-access papers:
PRRX1 is named in the same sentence as 118 diseases in open-access papers, as found by Europe PMC text mining. Sharing a sentence is not in itself a finding about the gene and the disease. The quoted sentences say what the papers report.
breast carcinoma (23 papers, 2017 to 2025). "Among these 4 upstream TFs, PRRX2, TWIST1, and PRRX1 were reported to induce mesenchymal–epithelial cell transformation and were associated with breast cancer metastasis." (PMID 37736108, 2023). "PRRX1 cooperates with Twist1 to induce EMT during embryogenesis and tumor invasion, but overexpression of PRRX1 is associated with a favorable prognosis in breast cancer patients." (PMID 35601657, 2022). "Similarly, intravenous injection of Prrx1 expressing breast cancer cells were more likely form metastases following loss of Prrx1." (PMID 30194451, 2019). "Next, PRRX1 expression was examined in various types of cancer, including colon, stomach, lung, esophageal, and breast cancers, using immunohistochemistry." (PMID 35589735, 2022). "Mechanistically, loss of PRRX1 induces MET, which is required for metastatic colonization of breast cancer cells." (PMID 35601657, 2022). "Based on their findings, the authors concluded that SIRT1 deacetylates and stabilizes PRRX1 to inhibit breast cancer stemness and metastasis." (PMID 36291902, 2022). "Some established oncogenes are also direct targets of miR-655 in other types of cancers, such as Prrx1 in breast cancer, ZEB1 and TGFBR2 in ESCC, ADAM10 in hepatocellular carcinoma, and PAX6 in retinoblastoma." (PMID 33643926, 2021). "For example, the overexpression of PRRX1 in human colon cancer cell lines induced EPH receptor B2 – an intestinal stem cell marker, whereas the knockdown of PRRX1 in breast cancer increased stemness features." (PMID 34496784, 2021). "For example, the EMT-promoted transcription factor PRRX1 suppresses stemness in breast cancer cells." (PMID 33953351, 2021). "PRRX1 has been demonstrated as a novel inducer of the epithelial-mesenchymal transition of tumor cells, such as breast cancer, colorectal cancer, and OC." (PMID 33563317, 2021). "For example, low expression of PRRX1 enabled metastatic colonization of lung by breast cancer cells." (PMID 34496784, 2021). "A significant positive correlation (R = 0.38, P = 0.0012) between nuclear SIRT1 and PRRX1 was observed in breast carcinomas." (PMID 30038266, 2018). "In breast cancer patients, decrease of SIRT1 was associated with reduced PRRX1 but increased KLF4, and the latter was positively correlated with distal metastases (P<0.001, χ2 test)." (PMID 30038266, 2018). "Collectively, our data support the notion that PRRX1 instability, at least partially, underlies SIRT1 deficiency-induced epithelial plasticity and CSC properties of breast cancers." (PMID 30038266, 2018). "Given that PRRX1 deficiency promotes MET and CSCs in breast cancer, we reasoned that re-introduction of PRRX1 would reverse MET and CSC-like phenotypes in SIRT1-depleted cells." (PMID 30038266, 2018). "In breast cancer, PRRX1 overexpression may induce multidrug resistance through the PTEN/PI3K/Akt signaling pathway and promote tamoxifen resistance in MCF-7 cells via EMT induction." (PMID 40860778, 2025). "To investigate downstream targets of PRRX1, we used MDA-MB-231 breast cancer cells which express low level of PRRX1 to generate a stable cell line where PRRX1 was ectopically overexpressed (MDA231-PRRX1), and performed comparative microarray analyses (GEO: GSE138078)." (PMID 31712603, 2019). "In clinical contexts, PRRX1 has been associated to contradictory prognostic outcomes showing that high PRRX1 expression predicted improved overall survival in colorectal cancer and HCC, but was associated with metastasis and poor survival outcome in breast cancer." (PMID 34496784, 2021). "Indeed, we found that PRRX1 declines along tumor progression and is stained negative in 78% metastases, making it alone a potential diagnostic biomarker for breast cancer." (PMID 30038266, 2018). "Prior research has established a robust link between elevated PRRX1 expression and the progression and recurrence of CRC, breast cancer, and esophageal cancer, leading to poor prognosis and drug resistance." (PMID 38846981, 2024).
breast carcinoma (continued). "PRRX1 alterations in liver cancer (i.e. HCC and cholangiocarcinoma) along with its alterations in lung, bladder and breast cancer cohorts, ranked very high (within top 10% of all TCGA cohorts)." (PMID 34496784, 2021). "For instance, some studies found EMT rather suppresses tumor-initiating abilities, i.e., suppression of PRRX1 promotes MET to enhance stemness and metastatic potential of breast cancers." (PMID 30038266, 2018). "A case in point is paired related homeobox 1 (Prrx1), which is an EMT-inducing factor but inhibits breast cancer cell metastasis." (PMID 28356139, 2017). "The protein expression of PRRX1, a transcription factor that induces epithelial-to-mesenchymal transition (EMT) and inhibits cancer stemness, was shown to be downregulated by SIRT1 gene silencing in mouse 4T1 breast cancer cells." (PMID 36291902, 2022). "In breast cancer, a SIRT1-PRRX1-KLF4-ALDH1 circuitry has been identified, in which SIRT1 deacetylases and stabilizes the epithelial-to-mesenchymal-transition inducer, PRRX1, by inhibiting its proteasomal degradation." (PMID 35745656, 2022). "Notably, COL6A3 and PRRX1 have been shown to confer resistance to chemotherapeutic agents like cisplatin, and circulating COL6A3 has been proposed as a prognostic biomarker for colorectal and breast cancers." (PMID 39920655, 2025). "Currently available reports have tried to explain RBMS3′s anticancer activity in all types of breast cancer through the inhibition of the Wnt/β-catenin pathway and the inhibition of the epithelial–mesenchymal transition process (EMT), mainly by impacting on TWIST, PRRX1, or MMP2." (PMID 36769184, 2023). "The currently postulated mechanisms explaining the role of RBMS3 in the progression of breast cancer include involvement in the epithelial–mesenchymal transition (EMT) by inhibiting the Wnt/β-catenin signaling pathway and other EMT-related transcription factors, such as TWIST1 or PRRX1." (PMID 36769184, 2023). "Importantly, the nuclear proportion of SIRT1 and PRRX1 are significantly correlated with each other, i.e., more than 90% metastases were nuclear SIRT1-PRRX1 double negative/low (P<0.001), supporting a SIRT1-PRRX1 axis in regulating breast cancer metastasis." (PMID 30038266, 2018). "Likewise, 40% (27 of 68) invasive ductal carcinoma, 68% (15 of 22) invasive lobular carcinoma and more than 94% (30 of 32) metastases were completely negative for PRRX1, whereas 90% (27 of 30) ductal/lobular carcinoma in situ and fibroadenoma were positive." (PMID 30038266, 2018).
pancreatic cancer (19 papers, 2016 to 2025). "The CCLE dataset revealed elevated expression of six module genes (GFPT2, MFAP5, CTSK, MMP2, FSTL1, and PRRX1) associated with poor overall survival in patients with pancreatic cancer." (PMID 40430018, 2025). "High stromal expression of transcription factor paired related homeobox 1 (Prrx1) in pancreatic cancers is associated with a more aggressive, squamous subtype of the cancer than cancers in other patients." (PMID 37046676, 2023). "Conditional Prrx1 loss of function in Sm22 (Tagln) positive CAFs in a mouse model of pancreatic cancer also promoted in vitro an activated phenotype with an increase in ACTA2 and COL1 expression levels." (PMID 37261432, 2023). "In conclusion, our study successfully identified a module of six key genes—GFPT2, MFAP5, CTSK, MMP2, FSTL1, and PRRX1—through Weighted Gene Co-expression Network Analysis (WGCNA) to assess cancer-associated fibroblast (CAF) infiltration in pancreatic cancer (PC)." (PMID 40430018, 2025). "Furthermore, PRRX1 was upregulated in various tumors, including colorectal cancer, pancreatic cancer and other cancers, and its expression was closely linked to malignant characteristics such as tumor cell stemness, invasiveness, and angiogenesis." (PMID 39896800, 2024). "High expression levels of Prrx1 in CAFs are associated with squamous subtypes of pancreatic cancer." (PMID 33333727, 2020). "Additionally, in a pancreatic cancer mouse model, Prrx1 conditional loss of function in cancer-associated fibroblasts, using a different Prrx1fl allele and the Sm22-CreERT driver mouse line, resulted in increased extracellular matrix deposition and the accumulation of myofibroblasts." (PMID 40856011, 2025). "Intriguingly, a specific clone of CAFs associated with ECM (eCAFs) is identified in pancreatic cancer and gastric cancer, and recently identified Endo180 and paired related homeobox 1 (Prrx1) may be significant genes associated with the function and plasticity of eCAFs." (PMID 36906534, 2023). "PRRX1, along with the cofactor FOXM1, was reported to activate the transcription of PRKDC, the gene encoding DNA-PKcs, in pancreatic cancer cells." (PMID 40114375, 2025). "Utilizing the CCLE database, it was confirmed that fibroblast cell lines exhibited elevated mRNA levels of the six module genes (GFPT2, MFAP5, CTSK, MMP2, FSTL1, and PRRX1) (accessed on 2 March 2025) compared to pancreatic cancer cell lines." (PMID 40430018, 2025). "In glioma and pancreatic cancer, Prrx1 is highly expressed in tumour-initiating cells and is involved in the regulation of invasion or metastasis." (PMID 38448751, 2024). "In glioma and pancreatic cancer, PRRX1 is overexpressed in tumor-initiating cells and plays a regulatory role in tumor invasion and metastasis." (PMID 35530319, 2022). "Evidence from prior studies in colon, breast, and pancreatic cancer support that PRRX1 has context-dependent functions – i.e. it can have a tumour promoter or suppressor function." (PMID 34496784, 2021). "PRRX1 (paired related homeobox 1), a homeodomain transcriptional factor, has been demonstrated to be important in pancreatic cancer, especially in the regulation of epithelial-to-mesenchymal transition (EMT) in pancreatic cancer." (PMID 34395285, 2021). "In Pdx1-Cre; lox-stop-lox-KrasG12D/+; Ink4alox/+ murine pancreatic cancer and in pancreatic cancer patient specimens, Prrx1 is expressed in CAFs." (PMID 33333727, 2020). "In pancreatic cancer, Prrx1 has two alternatively spliced isoforms, Prrx1a and Prrx1b, which are similar in structure but have different, even completely opposite functions." (PMID 31752959, 2019). "MiR-23b regulates autophagy and is also involved in radioresistance of pancreatic cancer, MiR-124 targets PRRX1 and sensitizes the radio-therapy of human colorectal cancer cells." (PMID 29285299, 2017).
pancreatic cancer (continued). "Recently, it was reported that up-regulated PRRX1 is closely correlated with metastasis and poor prognosis in colorectal and pancreatic cancers and enhances invasiveness in glioblastoma cell lines." (PMID 28033430, 2016). "Therefore, we analysed protein levels in MPNST, glioblastoma, pancreatic cancer and small cell lung cancer cell lines and confirmed the expression of PRRX1 and TOP2A." (PMID 38448751, 2024). "In the mRNA expression profiles analysed using the GEPIA Platform, PRRX1 and TOP2A were highly expressed in glioblastoma and pancreatic cancer as well as MPNST." (PMID 38448751, 2024). "The plasticity of CAFs in pancreatic cancer is mediated by transcription factor Prrx1, which is critical in CAF activation, in allowing a dynamic switch between a dormant and an activated state, and in exerting a significant impact on pancreatic cancer biology and therapeutic resistance." (PMID 37046676, 2023). "However, it is found that overexpression of PRRX1 is closely related to tumor EMT, tumor stemness, tumor metastasis, and prognosis in pancreatic cancer, colorectal cancer, and papillary thyroid cancer." (PMID 35530319, 2022). "Interestingly, PRRX1 could transcriptionally maintain the expressions of DDR genes including ATM, ATR, BRCA1, PRKDC, and XRCC1, in PANC1 pancreatic cancer cells." (PMID 40114375, 2025).
colorectal cancer (15 papers, 2014 to 2025). A primary or metastatic malignant neoplasm that affects the colon or rectum. "Meanwhile, low Prrx1 expression is significantly associated with poor prognosis in various digestive system tumours, including colorectal cancer, gastric cancer, and HCC." (PMID 31752959, 2019). "Finally, both miR-100 and miR-124 have been found to be associated with radiosensitivity in colorectal carcinoma trough targeting PRRX1 (Paired Related Homeobox 1)." (PMID 28325958, 2017). "In colorectal cancer, for instance, high PRRX1 expression correlates with metastasis, chemoresistance, and poor prognosis." (PMID 40860778, 2025). "PRRX1 upregulation promotes proliferation, stemness, and chemoresistance in colorectal cancer cells by activating the interleukin-6 (IL-6)/JAK2/STAT3 axis, with IL-6 inhibition reversing its effects on stemness and chemoresistance." (PMID 40860778, 2025). "In this research study, we have illustrated that miR-124 sensitized colorectal cancer cells to radiation treatment to some extent by downregulating PRRX1." (PMID 24705396, 2014). "Additionally, SPOCK1 upregulation in colorectal cancer cells enhances 5-fluorouracil resistance by regulating PRRX1 expression and downstream apoptosis signaling." (PMID 40860778, 2025). "Another transcription factor that regulates the EMT is the paired-related homeobox protein 1 (PRRX1), which activates EMT in various types of cancers, including colorectal cancers." (PMID 37239099, 2023). "However, opposite finding showed that upregulated PRRX1 induces EMT, cancer stemness, metastasis, and poor prognosis in colorectal cancer, suggesting the role of PRRX1 is highly context‐dependent in different tumor types." (PMID 35601657, 2022).
gastric cancer (12 papers, 2016 to 2025). A primary or metastatic malignant neoplasm involving the stomach. "In this study, we systematically delineated the transcriptional regulatory landscape of THY1 in gastric cancer by identifying six robust putative regulators—PRRX1, TWIST1, SNAI2, MEIS3, VENTX, and EGR2—through an integrative multicohort approach." (PMID 40476057, 2025). "Paired-related homeobox 1 (PRRX1) has been found to induce EMT in gastric cancer cells, NSCLC cells as well as in salivary adenoid cystic carcinoma cells." (PMID 34708244, 2022). "Mechanistically, PRRX1 was shown to induce EMT by activating the Wnt/β-Catenin pathway in gastric cancer cells." (PMID 34708244, 2022). "In gastric cancer, PRRX1 stimulates translocation of β-catenin into the nucleus upon Wnt pathway activation, thereby inducing c-Myc and consequent EMT of tumor cells." (PMID 32811812, 2020). "The fact that PRRX1 promotes EMT through the Wnt/β-catenin pathway in gastric cancer and that LGR5 is a co-receptor of the Wnt/β-catenin pathway involved in tumorigenesis clearly suggests an intimate association between PRRX1, LGR5 and EMT." (PMID 28033430, 2016). "PRRX1 might promote gastric cancer lymph node metastasis by regulating EMT, which in turn affected patient prognosis." (PMID 39896800, 2024). "The significant PRRX1 up-regulation observed in a variety of gastric cancer cell sources could explain the high malignancy and poor outcomes of gastric adenocarcinoma because PRRX1 is a strong driver of both EMT and metastasis." (PMID 28033430, 2016). "The regulatory function of TEAD4, ETV4, PRRX1, and FOXM1, over other key TFs and common DEGs, was highlighted in gastric cancer, establishing key co-regulatory complexes." (PMID 39228892, 2024). "Furthermore, exosomal circ-PRRX1 promotes cell proliferation in vitro and tumor growth in vivo by sponging miR-596 and activating the NF-κB signaling pathway in gastric cancer (GC)." (PMID 37525158, 2023). "PRRX1 is an exceptional EMT regulator because it is up-regulated in all cell sources, including gastric cancer tissues, gastric cancer cell lines and sphere cells." (PMID 28033430, 2016). "Since the qPCR analysis of gastric cancer tissues only detected up-regulated expression of LGR5, CD44 and PRRX1 among the putative CSC markers, stemness regulators and EMT inducers, we next tried to use GC cell lines in vitro to confirm this result." (PMID 28033430, 2016).